RNU4-2 (RNA, U4 small nuclear 2)
Synonyms: U4c; U4b; U4A; NEDHAFA; RENU; RNU4-1B; RNU4B1; RNU4C; RP102
Gene: Small nuclear RNA gene on chromosome 12 (120,291,759 to 120,291,903, reverse strand). Ensembl gene ENSG00000202538.
Gene Ontology:
Molecular function: U6 snRNA binding
Biological process: formation of quadruple SL/U4/U5/U6 snRNP; spliceosomal tri-snRNP complex assembly
Cellular component: U4 snRNP; U4/U6 x U5 tri-snRNP complex
Gene-disease validity (ClinGen):
ClinGen rates the evidence that RNU4-2 causes each of these diseases.
neurodevelopmental disorder with hypotonia, brain anomalies, distinctive facies, and absent language (autosomal dominant): Strong. A syndromic neurodevelopmental disorder in which the cause of the disease is a variation in RNU4-2 gene and is inherited in an autosomal dominant pattern.
Diseases named in the same sentence as RNU4-2 in open-access papers:
RNU4-2 is named in the same sentence as 4 diseases in open-access papers, as found by Europe PMC text mining. Sharing a sentence is not in itself a finding about the gene and the disease. The quoted sentences say what the papers report.
ReNU syndrome (5 papers, 2025 to 2026). "Genetic variants in RNU4-2, which is transcribed into the U4 small nuclear RNA component of the major spliceosome, were recently shown to cause ReNU syndrome, a prevalent dominant neurodevelopmental disorder (NDD)." (PMID 41951959, 2026). "Recently, de novo variants in an 18-nucleotide region in the centre of RNU4-2 were shown to cause ReNU syndrome, a syndromic neurodevelopmental disorder that is predicted to affect tens of thousands of individuals worldwide." (PMID 41951737, 2026). "ReNU syndrome is a rare but increasingly recognized syndromic neurodevelopmental disorder caused by heterozygous de novo variants in the non-coding gene RNU4-2, which encodes the U4 small nuclear RNA (snRNA), a critical component of the major spliceosome." (PMID 42285908, 2026). "De novo variants in snRNA genes RNU4-2 (ReNU syndrome), RNU5B-1 and RNU2-2 have been linked to dominant neurodevelopmental disorders (NDDs), revealing a large unexpected contribution of noncoding RNA genes to genetic diseases." (PMID 41912934, 2026). "Finally, we find reduced RNU4-2 transcript levels in individuals with the recessive disorder, suggesting a loss-of-function disease mechanism that is distinct from the mechanism underlying ReNU syndrome." (PMID 41951959, 2026). "These, along with the recently described RNU4-2-related ReNU syndrome, provide a genetic explanation for a substantial proportion of individuals with NDDs." (PMID 40442284, 2025).
neurodevelopmental disorder (8 papers, 2024 to 2026). A behavioral and cognitive disorder with onset during the developmental period that involves impaired or aberrant development of intellectual, motor, or social functions. "Mutations in a small noncoding gene called RNU4-2 are responsible for one of the most common neurodevelopmental disorders that is mediated by a single gene." (PMID 38821540, 2024). "The non-coding RNA RNU4-2, which is highly expressed in the developing human brain, is identified as a syndromic neurodevelopmental disorder gene, and, using RNA sequencing, 5′ splice-site use is shown to be systematically disrupted in individuals with RNU4-2 variants." (PMID 38991538, 2024).
RNU4-2 also shares sentences with these, for which no sentence is quoted: colon cancer (1 paper); genetic diseases (1).